NKX2-6 (NK2 homeobox 6)
Description:
Acts as a transcriptional activator. In conjunction with NKX2-5, may play a role in both pharyngeal and cardiac embryonic development.
Synonyms: NKX2F; CSX2; NKX4-2; CTHM
Tractability: No criterion of Open Targets' tractability assessment is met for any kind of drug.
Gene: Protein-coding gene on chromosome 8 (23,701,740 to 23,706,756, reverse strand). Ensembl gene ENSG00000180053.
Subcellular location: Nucleus
Subcellular location (Human Protein Atlas): Nuclear membrane; Cytosol; Nucleoplasm
Gene Ontology:
Molecular function: DNA-binding transcription activator activity, RNA polymerase II-specific; DNA-binding transcription factor activity; RNA polymerase II cis-regulatory region sequence-specific DNA binding; DNA-binding transcription factor activity, RNA polymerase II-specific; DNA binding
Biological process: embryonic heart tube development; positive regulation of transcription by RNA polymerase II; atrial cardiac muscle cell development; cell differentiation; digestive tract development; hypothalamus development; negative regulation of apoptotic process; pericardium development; pharyngeal system development; positive regulation of cell population proliferation; regulation of transcription by RNA polymerase II; tongue development; ventricular cardiac muscle cell development; regulation of DNA-templated transcription
Cellular component: chromatin; nucleus
Genetic constraint (gnomAD): Loss-of-function variants: 8 observed, 8.21 expected, observed/expected ratio (o/e) 0.97, 90% interval 0.57 to 1.69. That is too few expected variants to judge how well the gene tolerates losing a copy. Missense variants: 475 observed, 391.58 expected, observed/expected ratio (o/e) 1.21, 90% interval 1.12 to 1.31. Synonymous variants: 210 observed, 177.02 expected, observed/expected ratio (o/e) 1.19, 90% interval 1.06 to 1.33.
Gene-disease validity (ClinGen):
ClinGen rates the evidence that NKX2-6 causes each of these diseases.
congenital heart disease (autosomal recessive): Limited. A heart disease that is present at birth.
Homologues: Orthologues: chimpanzee NKX2-6 (99% identical), macaque NKX2-6 (94% identical), rabbit NKX2-6 (72% identical), pig NKX2-6 (72% identical), dog NKX2-6 (71% identical), mouse Nkx2-6 (58% identical), rat Nkx2-6 (58% identical), Drosophila melanogaster scro (31% identical), Caenorhabditis elegans ceh-22 (28% identical), Caenorhabditis elegans ceh-24 (28% identical), Drosophila melanogaster vnd (28% identical), Caenorhabditis elegans ceh-28 (22% identical), and 6 more. Paralogues in human: NKX2-3 (48% identical), NKX2-5 (43% identical), NKX2-4 (35% identical), NKX2-1 (32% identical), NKX2-2 (29% identical), NKX3-2 (28% identical), NKX2-8 (26% identical), NKX3-1 (23% identical), NKX1-1 (21% identical), NKX1-2 (21% identical), NKX6-1 (16% identical), NKX6-2 (15% identical), and 1 more.
Diseases named in the same sentence as NKX2-6 in open-access papers:
NKX2-6 is named in the same sentence as 12 diseases in open-access papers, as found by Europe PMC text mining. Sharing a sentence is not in itself a finding about the gene and the disease. The quoted sentences say what the papers report.
breast carcinoma (2 papers, 2019 to 2022). "Interestingly, promoter hypermethylation of NKX2-6 has been identified as a candidate biomarker associated with differential methylation in HER2+ breast cancer and breast carcinogenesis." (PMID 36612126, 2022). "In the current study, we identified and evaluated SPAG6, PER1 and NKX2-6 as novel epigenetic biomarkers for liquid biopsy-based early breast cancer detection." (PMID 31741713, 2019). "Accordingly, we identified SPAG6, PER1 and NKX2-6 as novel potential biomarkers for minimally invasive breast cancer detection." (PMID 31741713, 2019). "A combination of SPAG6 and NKX2-6 revealed a sensitivity of 27% for breast cancer detection (cut-off methylation 6.9%, 85% specificity), which could be increased to 31% using a combination of SPAG6 and PER1 (cut-off 7.7%, 85% specificity)." (PMID 31741713, 2019). "Based on TCGA analysis and the defined criteria, we identified ten potential candidate genes of which SPAG6, PER1 and NKX2-6 proved suitable for early breast cancer detection after an initial validation in breast cancer cell lines and a small cryoconserved tissue cohort." (PMID 31741713, 2019). "Although liquid biopsy remains challenging, a combination of SPAG6, NKX2-6, ITIH5 and PER1 (SNiPER) provides a promising tool for blood-based breast cancer detection." (PMID 31741713, 2019). "ROC curve analysis for NKX2-6 CpG3 revealed a sensitivity of 38% for DCIS detection, which was decreased to 25% for breast cancer detection, both at 84% specificity." (PMID 31741713, 2019). "The highest sensitivity for breast cancer detection was however achieved with a combination of SPAG6, PER1 and NKX2-6 (58% sensitivity, cut-off 4.2%, 79% specificity)." (PMID 31741713, 2019). "Basal-like breast cancers frequently show low methylation levels of tumor suppressor genes, single CpGs of SPAG6, PER1, NKX2-6 and ITIH5 however showed a higher methylation frequency in this molecular breast cancer subtype (59%, 42%, 52% and 41%, respectively)." (PMID 31741713, 2019). "Breast cancer patients showed a non-significant higher methylation frequency for SPAG6 (mean of 6.6% in benign controls versus 8.4% in breast cancer cases, p = 0.2536), PER1 (2.6% versus 4.8%, p = 0.5792), NKX2-6 (1.3% versus 2.9%, p = 0.1898) and ITIH5 (6.8% versus 5.9%, p = 0.9343)." (PMID 31741713, 2019). "However, increases in SPAG6, PER1, NKX2-6 and ITIH5 promoter methylation may not be confined to breast cancer and therefore needs to be tested in non-breast cancer patients such as colorectal- and lung cancer patients, the second and third most common cancers in women." (PMID 31741713, 2019).
congenital heart defects (2 papers, 2013 to 2021). "An additional three individuals were found to harbour pathogenic variants in genes associated with vascular abnormalities or congenital heart defects (TTN, NKX2-6 and ARHGAP31)." (PMID 34531397, 2021).
Thromboembolism (2 papers, 2021 to 2023). The formation of a blood clot inside a blood vessel that subsequently travels through the blood stream from the site where it formed to another location in the body, generally leading to vascular occlusion at the distant site. "Some research has proposed that genetic variations in these transcription factors were related to the higher risk of atrial fibrillation, suggesting that NKX2-6 mutations might also increase thromboembolism risk." (PMID 37626805, 2023).
benign breast disease (1 paper, 2019). "Since plasma shows lower cfDNA concentrations compared to serum, we tested the methylation frequency of SPAG6, PER1, NKX2-6 and ITIH5 in a plasma cohort, consisting of women with a benign breast disease (n = 14) and invasive breast cancer (n = 111)." (PMID 31741713, 2019).
invasive breast carcinoma (1 paper, 2019). A carcinoma that infiltrates the breast parenchyma. "We initially assessed promoter methylation of SPAG6, PER1, NKX2-6 and ITIH5 in a serum cohort consisting of samples of women with benign disease (n = 34), DCIS (n = 27) and early invasive breast cancer (n = 42)." (PMID 31741713, 2019). "Adding PER1 or NKX2-6 to the two-gene panel increases sensitivity for DCIS detection to 70%, although decreases sensitivity for early invasive breast cancer (39% and 41%, respectively) detection." (PMID 31741713, 2019).
NKX2-6 also shares sentences with these, for which no sentence is quoted: cancer (2 papers); tumor (2); atrial fibrillation (1); familial atrial fibrillation (1); hypertrophic cardiomyopathy (1); lung carcinoma (1); squamous cell carcinoma (1).